EHMT2 (euchromatic histone lysine methyltransferase 2)
Diseases named in the same sentence as EHMT2 in open-access papers (continued):
Sharing a sentence is not in itself a finding about the gene and the disease.
tumor (continued). "Finally, consistent with the important role of immune cells in the observed tumor suppression from EHMT2 inhibition and TGF-β1 inhibition in immunocompetent mice, treatment with either BRD4770 or vactosertib failed to inhibit tumor growth in immunodeficient NSG mice." (PMID 41366520, 2026). "Of note, a recent report surprisingly demonstrated enhanced tumor formation when initiating tumors with mutant Kras and EHMT2 knockdown, This is in direct contradiction to our findings using a genetic model to delete EHMT2 concurrent with KrasG12D in tumor initiation." (PMID 35983994, 2022). "Besides, we estimated EHMT2's tumor-promoting function in vivo using xenograft assay." (PMID 34344448, 2021). "In addition, multivariate analysis showed that patients with high tumor EHMT2 protein expression had significantly worse 5-year overall survival compared to patients with low tumor EHMT2 expression, and this was independent of other established prognostic factors." (PMID 33050946, 2020). "Notably, the combination of the indicated EHMT2 inhibitor and Erlotinib could robustly retard tumor growth in NSCLC/ER xenograft models by regulating the PTEN/AKT pathway." (PMID 29374157, 2018). "Similarly, the results of the tumor sphere formation assay indicated that treatment with UNC0638 or EHMT2 siRNA could reverse tumor resistance-mediated increases in the numbers of tumor spheres in HCC827/ER cells." (PMID 29374157, 2018). "Collectively, these results demonstrate that, similar to the genetic inhibition of EHMT2, pharmacological inhibition of EHMT2 and TGF-β1 results in tumor suppression and increased NK cell infiltration." (PMID 41366520, 2026). "For instance, the expression of writers such as EHMT2, readers such as BRD4, or erasers such as HDAC5 is high in tumor tissues." (PMID 39774014, 2025). "For instance, EHMT2 represses the expression of pro-inflammatory cytokines, such as TNF, in tumor cells to promote breast cancer recurrence." (PMID 38948355, 2024). "Previously, it was reported that patients with high tumor expression levels of EZH-2, EHMT2/G9a, KDM3A, KDM4B, and LSD1/KDM1A had significantly worse prognoses." (PMID 38785960, 2024). "Our study revealed that the expression levels of NAV1, EHMT2, SP1, SLC6A4, OPRD1, and CYP3A4 between the normal and tumor were statistically significant." (PMID 38352696, 2024). "Euchromatic histone-lysine N-methyltransferase 2 (EHMT2) methylates histone H3 lysine 9 to generate heterochromatin and inhibit tumor suppressor genes." (PMID 37686578, 2023). "When DZN was replaced by the EHMT2 inhibitor UNC0642 to upregulate the expression of ALDH2, the tumor volume became bigger than in the other two groups." (PMID 35477569, 2022). "To verify the CRC growth inhibitory effect of EHMT2 inactivation in vivo, we performed xenograft analysis with BIX01294 and found that the tumor size was reduced in the BIX01294 treatment group compared with that in the control group." (PMID 34972816, 2022). "Intriguingly, a wide EHMT2 bind peak was found around the promoter region of APC, a tumor suppressor that promotes the rapid degradation of β-catenin to negatively regulate Wnt–β-catenin signaling (circled by a red rectangle)." (PMID 34344448, 2021). "Furthermore, consistent with strong tumor suppression, we noted reduced Ki-67 staining in EMT6 tumors expressing Ehmt2 compared to those expressing NS shRNA from immunocompetent syngeneic BALB/c mice (Fig. EV5E,F)." (PMID 41366520, 2026). "EHMT2 controls Wnt signaling and in AT2 cells and impairs tumor initiation." (PMID 35983994, 2022). "EHMT2 activity functions similarly in primary AT2, as well as, Kras-transformed tumor cells, suggesting that TPCs may share functional features of their respective cell of origin." (PMID 35983994, 2022). "Furthermore, we knocked out EHMT2 expression using CRISPR/Cas9 in Hep3B and Huh1 cells and observed that the deletion of EHMT2 restrained cell proliferation in vitro and tumor growth in vivo." (PMID 34344448, 2021).
tumor (continued). "To examine whether EHMT2 expression is de-regulated in ERMS, and if it is functionally relevant in these tumor subtype, we first examined its expression in 16 ERMS patient tumor sections." (PMID 33252038, 2020). "Furthermore, the treatment of HN4 cells by BIX01294, an EHMT2 inhibitor, inhibited TGF-β-induced tumor sphere formation and CD44 protein expression." (PMID 33117703, 2020). "Moreover, we determined that genetic or pharmacological inhibition of EHMT2 expression enhanced TKI sensitivity and suppressed migration and tumor sphere formation in EGFR-TKI-resistant NSCLC cells." (PMID 29374157, 2018). "In the TCGA dataset, EHMT1 and EHMT2 are not differentially expressed in GATA3-ext tumours and do not show a segmentation pattern." (PMID 27588951, 2016). "However, whether EHMT2 is important for NK cell-mediated tumor suppression is not known." (PMID 41366520, 2026).
infection (17 papers, 2013 to 2025). The state of being infected such as from the introduction of a foreign agent such as serum, vaccine, antigenic substance or organism. "Overall, we found that cytoplasmic EHMT1 and EHMT2 associate with each other as well as the viral nucleoprotein upon infection." (PMID 39509467, 2024). "The epigenetic regulator euchromatic histone lysine methyltransferase 2 (EHMT2) is recognized as having a key role in modulating the organismal stress response to infections." (PMID 40472016, 2025). "At mechanistic level, we discovered that cytoplasmic EHMTs (EHMT1N/C and EHMT2) interact with and methylate the nucleoprotein of SeV upon infection." (PMID 39509467, 2024). "ChA was seen, through molecular docking simulations, to partly inhibit both STAT3 and EHMT2, whereas caffeic acid partly inhibited EHMT2, ensuring optimal host immune defense upon infection." (PMID 37513186, 2023). "EHMT1N/C interacts with cytoplasmic EHMT2 and methylates SeV-Nucleoprotein upon infection." (PMID 39509467, 2024). "In accordance with the results in the EHMT2-inhibited group, the RAVSMC number was also noticeably reduced after lenti-shEHMT2 infection for the indicated times." (PMID 32174799, 2020).
adenocarcinoma (5 papers, 2018 to 2023). A common cancer characterized by the presence of malignant glandular cells. "To assess whether the relationship between EHMT2 activity and cell state extends to human tumors, we used clinical adenocarcinoma specimens and assessed the association between EHMT2 transcript and cell lineage gene signatures in a panel of 546 LUADs." (PMID 35983994, 2022).
cardiovascular diseases (3 papers, 2020 to 2026). "Euchromatic histone-lysine N-methyltransferase 2 (EHMT2) has been implicated in cardiovascular diseases, yet its role in vascular remodeling remains incompletely understood." (PMID 42062573, 2026).
neurological disorders (3 papers, 2022 to 2025). "This review provides a comprehensive overview of the role of G9a/EHMT2, focusing on its structure and exploring the impact of its pharmacological and/or gene inhibition in various neurological diseases." (PMID 39763018, 2025).
vasculopathy (2 papers, 2020 to 2022). "Histone lysine methyltransferase EHMT2 also plays a role in vasculopathy and vascular inflammation." (PMID 35645372, 2022).
genetic disorders (1 paper, 2022). "Indeed, several EHMT2 LoF alleles have been reported without convincing evidence for involvement in human genetic disorders." (PMID 36551904, 2022).
EHMT2 also shares sentences with these, for which no sentence is quoted: head and neck squamous cell carcinoma (11 papers); acute myeloid leukemia (10); Anxiety (9); cervical cancer (8); diabetes (6); esophageal squamous cell carcinoma (6); medulloblastoma (6); acute lymphoblastic leukemia (5); brain cancer (5); depression (5); atherosclerosis (4); cognitive decline (4); neurodevelopmental disorder (4); renal cell carcinoma (4); endometrial cancer (3); Ewing sarcoma (3); lymph node metastasis (3); metabolic disease (3); myopia (3); neurodegenerative disease (3); oral squamous cell carcinoma (3); osteosarcoma (3); pancreatic ductal adenocarcinoma (3); Peritoneal Fibrosis (3); Prader-Willi syndrome (3); renal carcinoma (3); serous ovarian cancer (3); squamous cell carcinoma (3); thyroid cancer (3); acute myocardial infarction (2).
A further 101 diseases each share a sentence with EHMT2 in 2 papers or fewer.